RNU6-1 (RNA, U6 small nuclear 1)
Synonyms: U6; U6-1; RNU6; RNU6A; RP103
Gene: Small nuclear RNA gene on chromosome 15 (67,839,939 to 67,840,045, reverse strand). Ensembl gene ENSG00000206625.
Gene Ontology:
Molecular function: U4 snRNA binding
Biological process: formation of quadruple SL/U4/U5/U6 snRNP; spliceosomal tri-snRNP complex assembly
Cellular component: U4/U6 x U5 tri-snRNP complex; U6 snRNP
Homologues: Orthologues: dog U6 (100% identical), mouse Gm25064 (100% identical), rabbit RNU6-1 (100% identical), rat U6 (100% identical). Paralogues in human: RNU6-2 (100% identical), RNU6-3P (100% identical), RNU6-4P (100% identical), RNU6-5P (100% identical), RNU6-6P (100% identical), RNU6-9 (100% identical), RNU6-12P (99% identical), RNU6-13P (99% identical), RNU6-17P (99% identical), RNU6-18P (99% identical), RNU6-25P (99% identical), RNU6-32P (99% identical), and 1288 more.
Diseases named in the same sentence as RNU6-1 in open-access papers:
RNU6-1 is named in the same sentence as 18 diseases in open-access papers, as found by Europe PMC text mining. Sharing a sentence is not in itself a finding about the gene and the disease. The quoted sentences say what the papers report.
glioblastoma (5 papers, 2017 to 2024). The most malignant astrocytic tumor (WHO grade IV). "In glioblastoma multiforme (GBM), the expression levels of one small non-coding RNA (RNU6-1) and two microRNAs (miR-320 and miR-574-3p) are significantly associated with GBM diagnosis, with RNU6-1 potentially serving as an independent predictor for GBM diagnosis." (PMID 38528957, 2024). "The expression of RNU6-1 in serum exosomes may be used for the differential diagnosis between PCNSL and glioblastoma." (PMID 33816315, 2021). "In one study, various microRNA species, including RNU6-1, were present in serum exosomes from glioblastoma patients, but not non-cancer controls." (PMID 29383115, 2017).
glioma (2 papers, 2018). A benign or malignant brain and spinal cord tumor that arises from glial cells (astrocytes, oligodendrocytes, ependymal cells). "Interestingly, RNU6-1 is reported to be an up-regulated biomarker in another study that compared glioma to control serum." (PMID 29444091, 2018).
RNU6-1 also shares sentences with these, for which no sentence is quoted: cancer (5 papers); Alzheimer disease (1); amyotrophic lateral sclerosis (1); Anxiety (1); autoimmune disease (1); breast carcinoma (1); cannabis dependence (1); cognitive decline (1); food allergy (1); Hepatic steatosis (1); infection (1); malaria (1); migraine (1); psoriasis (1); steatosis (1); tumor (1).